CYP2D6 (cytochrome P450 family 2 subfamily D member 6 (gene/pseudogene))
Diseases named in the same sentence as CYP2D6 in open-access papers (continued):
Sharing a sentence is not in itself a finding about the gene and the disease.
malaria (37 papers, 2016 to 2026). Malaria is a serious and sometimes fatal disease caused by a parasite that commonly infects a certain type of mosquito which feeds on humans. "The impact of CYP2D6 polymorphism on community-wide malaria risk variation remains undetermined, despite the high prevalence of low-activity variants in some endemic settings." (PMID 36634044, 2023). "For example, it would be beneficial to perform joint pharmacogenetic typing of G6PD along with CYP2D6 when considering Vivax malaria control with primaquine, as G6PD deficiency can result in primaquine-induced hemolysis." (PMID 35217695, 2022). "In the samples as a whole, a total of 16 CYP2D6 alleles were observed and the most common genotype was *10B/*10B, which was identified in 36 samples, including one patient who had four episodes of malaria attack." (PMID 36217154, 2022). "The study sought to identify the association between CYP2D6 phenotype and recurrence of malaria in Korean patients." (PMID 36217154, 2022). "It is now known that for CYP2D6 there are more than 150 major allelic variants and large populations of individuals in endemic areas of malaria are believed to be affected by null or intermediate phenotypes of this enzyme." (PMID 34366834, 2021). "Several studies conducted in malaria endemic areas have observed an association between impaired CYP2D6 activity and relapse." (PMID 34357252, 2021). "A link between drug efficacy and metabolism through CYP2D6 is supported by recent animal and clinical studies, including the association of CYP2D6 poor metaboliser phenotype status with primaquine failure in controlled human malaria infections with P. vivax." (PMID 31324806, 2019). "The aim of this study was to investigate the association of CYP2D6 polymorphisms and inferred CYP2D6 phenotypes with malaria recurrence in patients from the Western Brazilian Amazon, following chloroquine/primaquine combined therapy." (PMID 29390987, 2018). "This study aimed to determine the current prevalence of both G6PD deficiency and CYP2D6 variants in representative populations in a malaria-endemic region of South Africa." (PMID 29558929, 2018). "This study assessed the prevalence of G6PD deficiency and two important CYP2D6 variants in representative pre-elimination settings in South Africa, to inform malaria elimination strategies." (PMID 29558929, 2018). "The strong evidence in favor of CYP2D6 enzyme variations on the outcome of malaria treatment comes from the association between the repeated relapses and the frequency of alleles associated with low PQ metabolism." (PMID 27467145, 2016). "The precise profiling of CYP2D6 alleles is critical for identifying patients who are likely to benefit from primaquine therapy, a standard treatment for preventing P. vivax relapse and, as a result, obstacle for malaria elimination." (PMID 41028863, 2025). "This is the first study to evaluate how the CPR/CYP2D6 genetic variability affects the clearance of P. vivax gametocytes, highlighting the importance of understanding how pharmacogenetic factors influence the risk of malaria transmission." (PMID 38411047, 2024). "Additionally, primaquine efficacy against malaria parasites was decreased in individuals with impaired cytochrome P450 2D6 (CYP2D6) activity due to genetic polymorphisms." (PMID 36508454, 2022). "These sources of genetic variation within CYP2D6 and genetic polymorphisms across the human genome create the potential to modify the phenotypic AS for probe drugs as well as drugs to treat malaria and other wide-ranging health conditions (implications are focused on PQ discussed in sections below)." (PMID 36457706, 2022). "This study assessed the safety and efficacy of 0.25 mg/kg single-dose primaquine added to artemether-lumefantrine standard regimen for reducing transmission of P. falciparum gametocytes in patients with uncomplicated malaria based on CYP2D6 alleles common in African Tanzanian." (PMID 35279143, 2022).
malaria (continued). "Previous studies, which had very few patients, suggested that polymorphisms in CYP2D6 might hinder malaria treatment and contribute to the relapse of P. vivax infections." (PMID 27467145, 2016). "Indeed, substantial variation in the frequencies of the CYP2D6 alleles may have a major effect on the current malaria treatment protocol outcomes." (PMID 34366834, 2021). "Thus, the association of CYP2D6 and relapse in malaria endemic areas is difficult to prove." (PMID 34357252, 2021). "Surveys in other Asian countries have shown an approximate 50% prevalence of the reduced activity CYP2D6 allele *10, which could translate into increased risk of PQ radical cure failure and repeated relapses, making interruption of transmission and malaria elimination difficult to achieve." (PMID 32394887, 2020). "We determined CYP2D6*4 and CYP2D6* genotypes and metabolizer phenotypes in 96 patients with suspected malaria in Venezuela and found intermediate or poor metabolizer phenotypes in ≈25% of cases." (PMID 40867022, 2025). "A few studies have addressed the direct impact of CYP2D6 enzyme activity on the gametocytocidal effect of PQ in malaria." (PMID 38411047, 2024). "Primaquine is a prodrug that requires conversion by the CYP2D6 enzyme to be effective against malaria." (PMID 37513742, 2023). "It is not clear if the available primaquine concentration in individuals with reduced CYP2D6 activity can sterilize gametocytes and hence reduce malaria transmission." (PMID 35279143, 2022). "Multiple episodes of P. vivax relapse were reported in a patient who was an intermediate metabolizer with less than 50% CYP2D6 activity and treated with high-dose primaquine (30 mg daily for 14 days) to prevent malaria recurrence." (PMID 36508454, 2022). "The predicted CYP2D6 metabolizer status provides important information for malaria control in a population previously uncharacterized for CYP2D6 metabolizer status." (PMID 35217695, 2022). "This study aimed to characterize G6PD and CYP2D6 genetic variations in vivax malaria patients from Yala province, a malaria-endemic area along the Thai–Malaysian border, and determine the biochemical properties of identified G6PD variants." (PMID 36508454, 2022). "While G6PD deficiency was discovered in approximately 8% of people living in malaria-endemic areas, impaired CYP2D6 activity was estimated to affect more than 20% of the population." (PMID 36508454, 2022). "Among them, the clinical impact of CYP2D6-dependent metabolism of primaquine should be included to respond whether the Brazilian national malaria control program can establish genetic-based strategies to monitor subpopulations at greater risk for malaria relapse." (PMID 34366834, 2021). "This highlights the importance of knowing the host G6PD and CYP2D6 activities for effective radical cure of relapsing malaria by primaquine." (PMID 31399061, 2019). "Overall, among the 171 malaria RDT-positive patients genotyped, prevalence of the CYP2D6*4, CYP2D6*10 and CYP2D6*17 mutant alleles was low with allelic frequencies of 0.02, 0.11 and 0.16, respectively." (PMID 31234865, 2019). "This study reports on the prevalence of G6PD deficiency as well as CYP2D6*4 and CYP2D7*17 mutations in a southern African malaria pre-elimination setting, with the aim of informing a low-dose PQ policy." (PMID 29558929, 2018). "When co-administering CYP2D6 inhibitors with other therapies to treat malaria or other inflammatory diseases, evaluating potential DDIs is essential, as they may affect the metabolism of CYP2D6 substrates." (PMID 41249771, 2025). "Conventional assays often fall short, as they do not capture the wide range of allele diversity found at the CYP2D6 locus, particularly in populations from malaria-endemic regions." (PMID 41028863, 2025). "Malaria patients’ response to primaquine treatment is contingent on the level of CYP2D6 activity." (PMID 40867022, 2025).
malaria (continued). "They further used the pattern of CYP2D6 dispersal to hypothesize how PQ may be metabolized and hence used to treat malaria in different populations." (PMID 36457706, 2022). "Primaquine is a prodrug requiring conversion by the CYP2D6 enzyme to be effective against malaria parasites, while the evidence for tafenoquine remains unclear." (PMID 36508454, 2022). "Primaquine is commonly used in the malaria endemic areas of Yunnan Province, yet the systematic survey on the genetic polymorphisms of CYP2D6 has been not conducted." (PMID 33743705, 2021). "The present study sought to characterize CYP2D6 genetic variation in Madagascar, where populations originated from admixture between Asian and African populations, vivax malaria is endemic, and PQ can be deployed soon to achieve national malaria elimination." (PMID 33959023, 2021). "Few investigations have addressed the frequency of CYP2D6*41 in malaria populations in Brazil." (PMID 34366834, 2021). "Safety, tolerability, CYP2D6 and G6PD variant data from this study support the deployment of the WHO-recommended SLD primaquine without G6PD testing in South African districts with low-intensity residual transmission aiming to eliminate malaria." (PMID 31234865, 2019). "Further, the low levels of CYP2D6 PM and IM is encouraging for the use of single low-dose PQ as an adjunct to current malaria control tools, and may accelerate efforts to eliminate malaria in South Africa." (PMID 29558929, 2018). "Additionally, primaquine efficacy is diminished in individuals who have impaired P450 2D6 (CYP2D6) activity, and around half of malaria patients may have poor or intermediate CYP2D6 metaboliser phenotypes in Thailand." (PMID 40274286, 2025). "The aim of the study was to investigate whether or not CYP2D6 single nucleotide polymorphisms rs1065852, rs38920-97, rs16947 and rs28371725 are unequally distributed in malaria by Plasmodium vivax individuals from the Brazilian Amazon region." (PMID 34366834, 2021). "Vivax malaria relapse following PQ treatment has predominantly been observed in patients carrying decreased function alleles such as CYP2D6*10, *36, and *41, and nonfunctional alleles such as CYP2D6*4 and *5 in various combinations giving rise to IM and PM phenotypes." (PMID 33959023, 2021). "Equally important is the elimination of mature P. falciparum gametocytes (less than 10% of the malaria cases in Brazil) by primaquine, since CYP2D6 activity may also impact the treatment of this species, ultimately influencing malaria transmission profiles in endemic areas." (PMID 34366834, 2021). "Therefore, a more comprehensive analysis of the CYP2D6 genetic variation may add valuable information regarding the malaria treatment outcome." (PMID 27467145, 2016). "For instance, the CYP2D6*4 allele was observed at a frequency of 14% in an urban admixed population from Aragua, a nonmalaria state, and in Amerindian populations at frequencies of 4.2%–42.5% from Zulia (nonmalaria state) and 1.7%–5.45% from Bolivar (malaria state)." (PMID 40867022, 2025). "Safety, tolerability, CYP2D6 and G6PD variant data from this study support the deployment of the WHO-recommended SLD primaquine without G6PD testing to advance malaria elimination in South African districts with low-intensity residual transmission." (PMID 31234865, 2019). "The relevance of CYP2D6 variants for gametocyte clearance remains to be established; we did not perform genotyping for CYP2D6 which requires larger sample volumes and therefore cannot determine its impact on gametocyte clearance or malaria transmission after PQ." (PMID 27825738, 2016). "Taken together, the CYP2D6*10, CYP2D6*2, and CYP2D6*41 frequencies in the five areas of the Brazilian Amazon suggest that they may not affect primaquine metabolism and, if so, ultimately, would not influence episodes of malaria relapses." (PMID 34366834, 2021).
vivax malaria (24 papers, 2016 to 2026). "In this study, the association between the CYP2D6 phenotype and the risk of vivax malaria relapse in Korean patients was investigated." (PMID 36217154, 2022). "This study found that patients deemed as intermediate metabolizers as determined by CYP2D6 enzyme activity had a higher risk of vivax malaria recurrence than did those deemed as normal or ultrarapid metabolizers." (PMID 36217154, 2022). "The purpose of this new investigation is to capture CYP2D6 variation as completely as possible, then to perform genetic association analyses with PQ metabolism and efficacy against vivax malaria." (PMID 35230160, 2022). "The findings support previous studies that suggested the association of CYP2D6 phenotype and the risk of relapse in patients with vivax malaria." (PMID 36217154, 2022). "In relapsed vivax malaria cases in Papua New Guinea, CYP2D6 enzyme activity was mostly deficient star alleles *3, *4, *5, *6, *7, and *8, which indicates the phenotype of poor metabolizer (PM)." (PMID 34823523, 2021). "The current study is the first one that attempts to analyse CYP2D6 polymorphisms in the entire coding region sequence in the blood specimen of relapsed vivax malaria patients in Yunnan." (PMID 33743705, 2021). "Mutation of CYP2D6*10 allele accounts for the highest proportion of vivax malaria cases in Yunnan Province." (PMID 33743705, 2021). "The current study aims to preliminarily reveal the association between the recurrence of vivax malaria in Yunnan Province and CYP2D6 gene mutation by analysing polymorphisms in the entire coding region of human CYP2D6 gene." (PMID 33743705, 2021). "To identify patients at a higher risk for recurrences and their CYP2D6 metabolizer status, we describe three cases of multiple vivax malaria relapses in individuals with impaired CYP2D6 metabolic activity followed up at a non-endemic area in Brazil." (PMID 34391426, 2021). "In this study, Whole Genome Sequencing (WGS) was conducted to investigate the polymorphisms of CYP2D6 gene in the vivax malaria cases, thereby revealing the association between human CYP2D6 gene polymorphisms and the relapsed cases of vivax malaria." (PMID 33743705, 2021). "Previous study has revealed the association between CYP2D6 gene polymorphism and the ineffective potency of PQ in the radical cure of vivax malaria." (PMID 34823523, 2021). "886C > T and CYP2D6*2 allele, which correspond to impaired PQ metabolizer phenotype, are most closely related to the relapse of vivax malaria." (PMID 33743705, 2021). "The WHO further advocated the personalized dosage of PQ therapy for the eradicative treatment of vivax malaria based on acquired understanding of patients’ CYP2D6 genetic polymorphism and heterogeneity of enzyme activity." (PMID 34823523, 2021). "Bennett and colleagues first associated genetic CYP2D6 variation with relapses of Plasmodium vivax malaria after PQ treatment." (PMID 31383656, 2019). "Here we describe multiple relapses of a case of vivax malaria acquired in West Africa that also appears to be associated with impaired CYP2D6 metabolism of PQ." (PMID 31399061, 2019). "Taken together, the estimated frequencies of these primaquine ineligibles due to G6PD toxicity or impaired CYP2D6 activity composed over 35% of the populations at risk of vivax malaria." (PMID 29357870, 2018). "The results suggest that CYP2D6 polymorphisms are associated with increased risk of recurrence of vivax malaria, following chloroquine–primaquine combined therapy." (PMID 29390987, 2018). "This nested case-control study explores the association of impaired CYP2D6 genotype and metabolic phenotype activity with failure of high-dose primaquine treatment for Plasmodium vivax malaria relapse in Indonesian men." (PMID 30646129, 2018).
vivax malaria (continued). "We analyzed community-wide P. vivax malaria incidence data, using a multivariable negative binomial regression model, to quantify the impact of reduced CYP2D6 activity on the overall risk of vivax malaria, whether from relapses or new infections." (PMID 41894411, 2026). "However, it highlights the fact that in these vivax malaria endemic areas, even if CYP2D6 polymorphisms did play a key role, relatively few patients are null metabolisers." (PMID 36472067, 2022). "Therefore, vivax malaria patients with the defective CYP2D6 function would be at increased risk for therapeutic failure (relapses) regardless of proper treatment regimens with primaquine." (PMID 34391426, 2021). "Accumulating evidence suggest that compromised CYP2D6 enzyme activity caused by gene mutation could contribute to primaquine failure for the radical cure of vivax malaria." (PMID 33743705, 2021). "Since the effectiveness of PQ for radical cure of vivax malaria is influenced by host CYP2D6 activity, we wanted to determine whether the failure of PQ in this case might be linked to CYP2D6 genotypes suggestive of poor metabolizer of PQ." (PMID 31399061, 2019). "Genetic variation in CYP2D6, the gene producing the drug-metabolizing enzyme cytochrome P450 2D6 (CYP2D6), influences plasma concentrations of PQ and its metabolites and is associated with PQ treatment failure in Plasmodium vivax malaria." (PMID 31383656, 2019). "The aim of this study was to determine the CYP2D6 profile in a subset of ADF personnel deployed to PNG and East Timor and to explore whether their CYP2D6 activity can explain PART failure causing relapsing vivax malaria." (PMID 30999967, 2019). "It is hypothesized that Plasmodium vivax malaria patients with defective CYP2D6 function would be at increased risk for primaquine failure to prevent recurrence." (PMID 29390987, 2018). "Therefore, the profile of G6PD and CYP2D6 polymorphisms in this population should be characterized in order to provide information about the safety and efficacy of using 8-aminoquinolines in the treatment of vivax malaria." (PMID 36508454, 2022). "Recently, for the first time, the authors investigated CYP2D6 genetic variation in Madagascar, where vivax malaria is endemic." (PMID 35230160, 2022). "Impaired CYP2D6 affecting primaquine biotransformation is another challenge for effective radical cure of vivax malaria." (PMID 36508454, 2022). "In another study, an IM subject (genotyped as CYP2D6*5/*41) suffered multiple attacks of vivax malaria at approximately two-month intervals despite taking PQ as prescribed." (PMID 33959023, 2021). "In this context, we sought to investigate the possible contribution of CYP2D6 variation to relapses of vivax malaria." (PMID 27467145, 2016). "Although the present study supports the role of the host CYP2D6 metabolizer status on vivax malaria treatment’s outcome, this study has some limitations." (PMID 27467145, 2016). "Some studies suggest that CYP2D6 IMs or PMs may respond poorly to the radical cure treatment of vivax malaria, resulting in recurrences." (PMID 39858601, 2025). "Variations in the genetic background of Cytochrome P450 2D6 (CYP2D6), for example, influence the metabolism of primaquine, an 8-aminoquinoline used to prevent relapses of vivax malaria, affecting how this drug is metabolised and impacting treatment outcomes in a given individual." (PMID 41417553, 2025). "Our findings provide insights about genetic variations of G6PD and CYP2D6 in 88 vivax malaria patients from Yala, which may influence the safety and effectiveness of radical treatment." (PMID 36508454, 2022). "CYP2D6-dependent metabolism of primaquine may be a key determinant of the anti-hypnozoite activity of primaquine that prevents vivax malaria relapse." (PMID 36217154, 2022).